NDUFS4 (NADH:ubiquinone oxidoreductase subunit S4)
Diseases named in the same sentence as NDUFS4 in open-access papers (continued):
Sharing a sentence is not in itself a finding about the gene and the disease.
Leigh syndrome (continued). "Using the Ndufs4 knockout (Ndufs4 KO) mouse, a model of Leigh syndrome, it was demonstrated that protein succination increased in the brainstem (BS)." (PMID 34884639, 2021). "Microglia-located LD formation was also observed in a mouse model of Leigh Syndrome (deletion of Ndufs4, a mitochondrial Complex I subunit;), ageing brain, and in LPS-treated N9-treated microglia." (PMID 33671212, 2021). "Hypoxia, which was shown to be beneficial in mouse models of NDUFS4−/− Leigh syndrome, resulted in increased glycolysis and exacerbated the neuronal outgrowth phenotypes in the SURF1 neurons." (PMID 34299348, 2021). "Genetic or pharmacological activation of the HIF pathway in cellular and zebrafish models, as well as chronic normobaric hypoxic treatment in the murine Ndufs4 ko model of Leigh syndrome, prevented the development of the disease." (PMID 33187380, 2020). "Humans harboring mutations in NDUFS4, a subunit of the mitochondrial complex I involved in the assembly and stability of the complex develop Leigh Syndrome (LS), a severe form of MD." (PMID 32850799, 2020). "We first designed a single guide RNA (sgRNA) targeting exon 2 of Ndufs4 to delete the NDUFS4 protein in mouse embryos to mimic Leigh syndrome." (PMID 28533980, 2017). "In this study, we first generated Ndufs4 KO mice with physical and behavioral phenotypes similar to Leigh syndrome using the CRISPR/Cas9 system." (PMID 28533980, 2017). "The Ndufs4 knockout (NKO) mouse is a rodent model of human Leigh Syndrome, which develops progressive necrotizing encephalopathy of the vestibular nuclei, cerebellum, and olfactory bulb." (PMID 28919908, 2017). "In a recently published study, we reported a striking suppression of Leigh Syndrome phenotypes by rapamycin in Ndufs4 KO animals." (PMID 26257774, 2015). "Recently, we reported that daily intraperitoneal injection of rapamycin at 8 mg/kg attenuates mitochondrial disease symptoms and progression in the Ndufs4 knockout mouse model of Leigh Syndrome." (PMID 26257774, 2015). "Our observations indicate that the commonly used 14 PPM dose is significantly lower than necessary to observe robust effects on developmental weight gain and attenuate disease in the Ndufs4 KO mouse model of Leigh Syndrome." (PMID 26257774, 2015). "Patients with NDUFS4 and NDUFS7 mutations almost invariably have Leigh syndrome, in patients with NDUFS7 mutations, the brainstem is often affected." (PMID 22644603, 2012). "Notably, mutations in the nDNA-encoded NDUFS4 gene, encoding subunit four of CI, induce ’mitochondrial complex I deficiency, nuclear type 1′ (MC1DN1), and Leigh syndrome in pediatric patients." (PMID 40149709, 2025). "This study focuses on the Ndufs4 KO mouse model of Leigh syndrome." (PMID 39965572, 2025). "It is interesting that, similar to Riknull animals, mice deficient in a subunit of mitochondrial complex I, NADH:ubiquinone oxidoreductase core subunit S4 (Ndufs4), which is a model of Leigh syndrome, were born healthy, but by P21, they lagged behind in growth, developed ataxia and died prematurely." (PMID 39631040, 2024). "Importantly, the disease present in Ndufs4 KO closely resembles the one found in patients with Leigh syndrome." (PMID 38212783, 2024). "For instance, in the case of Leigh syndrome (LS), one of the most common and severe mitochondrial diseases, pre-clinical studies testing small molecules showed remarkable therapeutic effects in Ndufs4−/− mice." (PMID 38732047, 2024). "Furthermore, recent studies have highlighted the emerging role of microglia and peripheral immune cells in the development of the Ndufs4 KO encephalopathy, a mouse model of Leigh syndrome (LS)." (PMID 38212783, 2024). "Mice missing the Complex I subunit NDUFS4 are a leading mammalian model of Leigh Syndrome." (PMID 36799301, 2023). "Isoflurane is toxic in the Ndufs4(−/−) model of Leigh syndrome." (PMID 37770252, 2023).
Leigh syndrome (continued). "Similarly, we have previously shown that in the Ndufs4 KO mouse model of Leigh syndrome, chronic, continuous 11% O2 can prevent the onset of neurological disease, but ultimately, those mice also prematurely succumb to their cardiac pathology." (PMID 37260376, 2023). "Current mouse models have limitations and do not fully recapitulate the complexity of human disease phenotypes; however, the Leigh syndrome Ndufs4 knockout mouse model seems to exhibit the phenotype and neuropathological lesions in the brain regions relevant to the disease, such as the brainstem." (PMID 37298649, 2023). "For example, systemic delivery of a gene-replacement therapy with AAV-PHP.B (the parental serotype of AAV-PHP.eB) provided significant benefit in an Ndufs4 knockout mouse model of Leigh syndrome, where previous attempts using AAV163 and AAV2/964 serotypes resulted in less improvement." (PMID 35474956, 2022). "Knock-out mouse models (Ndufs4 KO) are widely used to study Leigh syndrome (LS)." (PMID 34069703, 2021). "Thus far, investigations have been reported for Leigh syndrome iPSC-derived neuronal cell types possessing mutations in: MT-ATP6, MT-ND5, NDUFS4 and SURF1, and SCO2." (PMID 34299348, 2021). "Hypoxia markedly improved lifespan (from 58 to 270 days), body weight, body temperature, behavior, neuropathology, and disease biomarkers in Ndufs4 ko mouse, a model of severe infantile Leigh syndrome; on the contrary, hyperoxia (55% O2) worsened all the parameters analyzed." (PMID 33187380, 2020). "If humans with Leigh syndrome have a similar defect in HPV as Ndufs4−/− mice, then this defect may contribute to the high mortality of patients with Leigh syndrome." (PMID 30520688, 2019). "NDUFS4 inactivation leads almost invariably to Leigh syndrome and neurological symptoms." (PMID 29590638, 2018). "Mice or humans lacking Ndufs4 have reduced Complex I levels and activity, and mutations in Ndufs4 cause Leigh Syndrome in humans." (PMID 28919908, 2017). "In our study, we attempted to investigate embryonic development in Ndufs4 KO mice, which can be regarded as a Leigh disease model and were created through the CRISPR (clustered regularly interspaced short palindromic repeat) and Cas9 (CRISPR associated)-mediated genome editing system." (PMID 28533980, 2017). "In this paper, we first obtained Ndufs4 KO mice that could mimic Leigh syndrome using the CRISPR/Cas9 system." (PMID 28533980, 2017). "Altogether, we verified that the Ndufs4 KO mice generated using the CRISPR/Cas9 system could mimic Leigh syndrome and function as a disease model." (PMID 28533980, 2017). "Thus, we aimed at validating whether this vulnerability is conserved in animals that constitutively lack NDUFS4 (KO mice), an established model of Leigh syndrome." (PMID 41321311, 2025). "Notably, it includes only a single patient with NDUFS4-related Leigh syndrome." (PMID 41573538, 2025). "A clear demonstration of the crucial role of mitochondrial complex I (CI) in embryo development comes from the characterization of the constitutive Ndufs4 knockout (KO) mouse model of Leigh syndrome (LS)." (PMID 39313811, 2024). "In this study, we examined the permeability of the BBB in the Ndufs4−/− mouse model of Leigh syndrome (LS)." (PMID 38732047, 2024). "The Ndufs4−/− Leigh Syndrome (LS) mice had normal left ventricular mass and Ejection Fraction as measured by echocardiography in conscious mice without an anesthetic agent." (PMID 37237867, 2023). "Mice with a germline deletion of Ndufs4 subunit respiratory complex I develop severe mitochondrial encephalomyopathy resembling Leigh Syndrome (LS)." (PMID 37237867, 2023). "The current study aims to elucidate the mechanistic role of oxidative stress in bradyarrhythmia in mitochondrial cardiomyopathy using mice with a germline deletion of a mitochondrial complex I subunit, Ndufs4, resembling Leigh Syndrome (LS)." (PMID 37237867, 2023).
Leigh syndrome (continued). "Mice with deletion of complex I subunit Ndufs4 develop mitochondrial encephalomyopathy resembling Leigh syndrome (LS)." (PMID 35872650, 2022). "Deletion of the iron–sulfur CI protein subunit, Ndufs4, leads to subsequent CID, and a progressive encephalomyopathy with severe musculoskeletal symptoms and poor prognosis known as Leigh syndrome (LS)." (PMID 34677373, 2021). "For example: Huntington’s disease (NDUFA7, NDUFC1, NDUFB2, NDUFB3, NDUFA8), atrophy of optic nerve (NDUFS4) and Leigh syndrome (NDUFS7, NDUFA2, NDUFS4)." (PMID 23028713, 2012). "Ndufs4(-/-) mouse model is considered the premier model for Leigh syndrome, and currently there are no other established mouse models of this disease." (PMID 39930437, 2025). "Among these models, studies in a mouse model of Leigh syndrome lacking the complex I subunit NDUFS4 have been instrumental in identifying the involvement of GABAergic neurons in the development of epileptic events." (PMID 41321311, 2025). "Although repeated acute intermittent hypoxia has been used to therapeutic effect in the C2 hemi-section model of spinal cord injury, intermittent hypoxia (10 h 11% oxygen, 14 h 21% oxygen) was not beneficial in the Ndufs4 KO mouse model of Leigh syndrome." (PMID 37220109, 2023). "In the Ndufs4 knockout mouse model of Leigh syndrome, NDI1 expression rescues the lifespan but not motor defects, potentially through regenerating mitochondrial NAD+ from NADH." (PMID 37399212, 2023). "Recently, the effects of the expression of NDI1 in vivo have been tested in a mouse model of Leigh syndrome due to the lack of the 18-KDa complex I subunit Ndufs4." (PMID 33187380, 2020). "Mice lacking Ndufs4, a protein which is responsible for the assembly and normal function of CI, serve as a model of Leigh syndrome." (PMID 30520688, 2019). "Mice lacking the mitochondrial complex I (CI) subunit Ndufs4 (Ndufs4−/−) develop a fatal progressive encephalopathy and serve as a model for Leigh syndrome, the most common mitochondrial disease in children." (PMID 30520688, 2019). "Lack of NDUFS4, a subunit of mitochondrial complex I (NADH:ubiquinone oxidoreductase), causes Leigh syndrome (LS), a progressive encephalomyopathy." (PMID 26824698, 2016). "Expression of the AAV-mitoTag in the glutamatergic vestibular neurons of a mouse model of Leigh Syndrome lacking the complex I subunit Ndufs4 allowed us to assess the proteome and acetylome of a subset of susceptible neurons in a well characterized model recapitulating the human disease." (PMID 32850799, 2020). "This might indicate that the Ndufs4(-/-)/Il2rg(KO) mice are more frail than Ndufs4(-/-)/Il2rg(+/-) animals, which would be consistent with the possibility that adaptive immune depletion not only fails to prevent disease but is actively harmful to the Leigh syndrome model." (PMID 40493653, 2025). "Similar defects were observed in iPSC-NPCs derived from two NDUFS4−/− iPSC lines (OXPHOS complex I subunit; Table A1), supporting the decreased branching and neurite length as a broader Leigh syndrome phenotype rather than being gene-specific." (PMID 34299348, 2021).
Ataxia (9 papers, 2008 to 2025). Ataxia refers to impaired coordination of voluntary muscle movement. "Ndufs4−/− (LS) mice have features of growth retardation, lethargy, cerebellar ataxia, loss of motor function due to both encephalopathy and myopathy, hypothermia, slowed breathing, and apnea." (PMID 37237867, 2023). "Similar results have been observed in other animal models of cerebellar ataxia, in the hippocampus of patients with Alzheimer’s disease and in the brain of Ndufs4−/− and mutator mice models of MD." (PMID 37446148, 2023). "The difference between age of onset of ataxia in Ndufs4(-/-)/Il2rg(KO) mice and Ndufs4(-/-)/l2rg(WT) mice was statistically significant, but so small it is unlikely to be biologically meaningful." (PMID 40493653, 2025). "Although Ndufs4-KO mice are small, they appear healthy until around 5 weeks of age, after which they begin to exhibit symptoms such as ataxia, and they have a median lifespan of 55 days." (PMID 39858433, 2024). "The Ndufs4−/− have reduced body weight and temperature, ataxia, seizures, lethargy, blindness, and irregular breathing." (PMID 34656053, 2022). "Ndufs4−/− mouse manifests specific symptoms similar to those found in the patients, including growth retardation, ataxia, hypotonia, lethargy, failure to thrive and breathing irregularities." (PMID 28753212, 2017). "Interestingly, ectopic expression of the yeast NADH dehydrogenase NDI1 in the brain rescued the lifespan of the brain-specific Ndufs4 knockout, but the mice still had severe ataxia." (PMID 34656053, 2022). "NDUFS4 knockout mice exhibit severe RCCI with features similar to those of Hq mice (growth retardation, blindness, ataxia, and baldness) but greater disease severity leading to death at 7 weeks of age after only 2 weeks with symptoms." (PMID 18791645, 2008).
hypertrophic cardiomyopathy (8 papers, 2014 to 2026). A condition in which the myocardium is hypertrophied without an obvious cause. "The myocyte-specific loss of Ndufs4 (driven by CKM-NLS-Cre) displayed features of hypertrophic cardiomyopathy." (PMID 37237867, 2023). "The deficiency of Ndufs4 is associated with hypertrophic cardiomyopathy, as well as leukoencephalopathy and lethal infantile mitochondrial disease." (PMID 33287280, 2020). "NDUFS4‐related LS, while characterised by neurological dysfunction, demonstrates significant cardiac involvement with hypertrophic cardiomyopathy documented in approximately 25% (8 of 32) of described cases." (PMID 41532297, 2026). "Selective NDUFS4 gene deletion in the heart reduces complex I activity by 50%, leading to severe hypertrophic cardiomyopathy." (PMID 38546629, 2024). "Another study demonstrated that Ndufs4-null mice had a decrease of about 50% in cardiac CI activity and developed severe hypertrophic cardiomyopathy as assessed by magnetic resonance imaging." (PMID 37558995, 2023). "In two independent studies describing mice with cardiac‐specific Ndufs4 deletion, one showed hypertrophic cardiomyopathy, while the other reported normal cardiac function." (PMID 35872650, 2022). "Ndufs8, like Ndufs4, is a peripheral membrane protein which can contribute to hypertrophic cardiomyopathy." (PMID 33287280, 2020). "Heart-specific Ndufs4-null mice had a decrease of ∼50% in complex I activity within the heart, and developed severe hypertrophic cardiomyopathy as assessed by magnetic resonance imaging." (PMID 24705922, 2014). "Here we demonstrate that selective disruption of the Ndufs4 gene in the heart leads to a ∼50% decrease in complex I activity, that in turn drives severe hypertrophic cardiomyopathy, as determined by magnetic resonance imaging (MRI)." (PMID 24705922, 2014). "Myocyte‐specific (Ckmm‐NLS) Ndufs4 KO mice display heart enlargement without clinical symptoms for up to 12 months, while another study reports hypertrophic cardiomyopathy without signs of oxidative stress." (PMID 41532297, 2026).
cardiomyopathy (6 papers, 2022 to 2026). A disease of the heart muscle or myocardium proper. "Human‐induced pluripotent stem cell‐derived cardiomyocytes (iPS‐CMs) with Ndufs4 deletion recapitulate LS cardiomyopathy." (PMID 35872650, 2022). "In contrast, whole‐body Ndufs4 KO mice do not develop cardiomyopathy but exhibit severe bradyarrhythmia with sinoatrial nodal dysfunction, a defect specifically attributed to Ndufs4 deficiency in conduction cells (HCN4)." (PMID 41532297, 2026).
Encephalopathy (6 papers, 2018 to 2024). Encephalopathy is a term that means brain disease, damage, or malfunction. "Our findings of LS human brain pathology, Ndufs4-deficient mouse and iPSC-neurons and brain organoid models of LS suggest a critical role of activated microglia in the progression of LS encephalopathy." (PMID 36741056, 2022). "Mice with homozygous Ndufs4 inactivation develop a severe encephalopathy resembling LS that results in death between 50 and 60 postnatal (P) days." (PMID 30979712, 2019).
Parkinson disease (6 papers, 2012 to 2022). A progressive degenerative disorder of the central nervous system characterized by loss of dopamine producing neurons in the substantia nigra and the presence of Lewy bodies in the substantia nigra and locus coeruleus. "Here, we investigated the effect of reduced complex I activity on non-motor symptoms associated with Parkinson’s disease using conditional knockout (cKO) mice in which Ndufs4 was selectively deleted in dopaminergic neurons (Ndufs4 cKO)." (PMID 28327638, 2017). "However, test animals lacking the Ndufs4 gene coding for a vital subunit of Complex I did not present Parkinson’s disease symptoms, nor did Complex I dysfunction cause neuronal death." (PMID 36012337, 2022). "Finally, a recent study shows that Ndufs4 deletion in dopaminergic neurons causes Parkinson’s disease-like non-motor symptoms without neuronal loss, likely due to reduced dopamine brain levels." (PMID 28883788, 2017). "In general, levodopa inhibited the growth of ESCC cells through regulating pathways involved in oxidative phosphorylation, NAFLD, and Parkinson disease, down-regulating the levels of SDHD, NDUFS4, and MT-CO3, and inhibiting oxidative phosphorylation." (PMID 33101026, 2020). "Furthermore, even though motor behavior were not affected, Ndufs4 cKO mice showed non-motor symptoms experienced by many Parkinson’s disease patients including impaired cognitive function and increased anxiety-like behavior." (PMID 28327638, 2017).
encephalomyopathy (5 papers, 2017 to 2026). "Mice with a homozygous germline deletion of exon 2 of the encoding gene (Ndufs4−/−) exhibit phenotypes resembling the severe encephalomyopathy in LS patients." (PMID 35872650, 2022). "Ndufs4 knockout (Ndufs4-KO) mice develop a severe and progressive encephalomyopathy that becomes apparent at about 40 days of age." (PMID 35668433, 2022). "In Ndufs4−/− mouse models, while the encephalomyopathy is unequivocal, cardiac involvement remains debatable." (PMID 35872650, 2022).
heart failure (5 papers, 2019 to 2023). Inability of the heart to pump blood at an adequate rate to meet tissue metabolic requirements. "A genetic model of mitochondrial complex I dysfunction (Ndufs4; cKO) was shown to be more susceptible to heart failure which was accompanied with increased NADH/NAD+ ratio and protein hyperacetylation." (PMID 34513955, 2021). "Inhibition of complex I through inactivation of the gene for the nuclear-encoded complex I subunit Ndufs4 facilitates the development of heart failure following pressure overload." (PMID 30838215, 2019). "Administration of NMN or overexpressing NAMPT normalized NADH/NAD+ ratio and reduced protein acetylation; and thus prevented heart failure in the Ndufs4 cKO and chronic pressure overload models." (PMID 34513955, 2021). "In summary, our results provide mechanistic information about the roles of previously studied genes namely, NDUFS4, LRPPRC, and COQ7, in heart failure." (PMID 37276142, 2023).